RXRA (retinoid X receptor alpha)
Diseases named in the same sentence as RXRA in open-access papers (continued):
Sharing a sentence is not in itself a finding about the gene and the disease.
tumor (continued). "To explore the role of RXRA in DANCR-mediated TNBC tumor growth, we first assessed RXRA protein and expression in DANCR depletion TNBC cells." (PMID 30518934, 2018). "Immunostaining of PyMT tumour specimens using Δ197 anti-RXRα antibody that recognizes both RXRα and tRXRα revealed a predominant cytoplasmic RXRα staining." (PMID 28714476, 2017). "We further confirm, through interrogation of multiple engineered lines and clinical data sets, that tumor-intrinsic PPARγ/RXRα pathway activity inhibits host immune response through suppressing expression and secretion of inflammatory factors." (PMID 28740126, 2017). "Our results revealed that the L-OHP content in tumor cells stably transfected with PXR or PXR + RXRA was on average significantly lower than that in tumor cells transfected with empty vector in both HCT116 and LOVO cells." (PMID 28356150, 2017). "A translational limitation of our study on RXRα status in human tumor specimens was the use of a commercial tissue microarray." (PMID 27167203, 2016). "In summary, our results show that energetic heavy ion radiation is capable of lowering RXRα in tumor as well as non-tumor intestinal epithelial cells." (PMID 26500891, 2015). "Our result demonstrates for the first time that RXRα is downregulated in tumor-free areas of APCMin/+ intestine ~100 days after radiation exposure." (PMID 26500891, 2015). "We also performed immunohistochemistry for RXRα on tumor-free intestinal sections from APCMin/+ mice exposed to either 1.6 or 4 Gy 56Fe ions." (PMID 26500891, 2015). "We first showed that expression of RXRα and t-RXRα in normal tissues was different from that in tumor tissues." (PMID 26450852, 2015). "Staining of tumor-free intestinal section showed lower expression of RXRα after 4 Gy 56Fe relative to corresponding controls." (PMID 26500891, 2015). "In subjects exposed to etodolac with pre- and postexposure flash frozen tumor available (n = 15), we evaluated the gene expression levels associated with the COX-2 pathway (COX-2 and β-catenin) and the RXRα pathway (RXRα, PPARγ, and cyclin D1)." (PMID 26275572, 2015). "Protein and gene expression levels for genes related to COX-2 and RXRα were evaluated in tumor samples from before and after etodolac exposure." (PMID 26275572, 2015). "Although these findings do not provide a definitive target, it can be postulated that celecoxib, through its direct inhibition of PDK-1, and sulindac, via its interaction with RXRα, are able to downregulate Akt-dependent tumor cell invasion." (PMID 23875171, 2013). "The R-enantiomer of etodolac, which lacks COX-inhibitory activity, has been shown to bind RXRα and selectively induce apoptosis in tumor cell lines." (PMID 23875171, 2013). "In a xenograft mouse model of NB and a cohort of patient samples, the formation of tripartite GRP75/RARα/RXRα complexes was inversely correlated with tumor progression and consistently predicted a favorable outcome." (PMID 22022577, 2011). "The correlation between the level of GRP75/RARα/RXRα tripartite complexes and tumor growth was further analyzed in the harvested NB xenografts." (PMID 22022577, 2011). "Gene expression data highlighted the PPARα/RXRα Activation Pathway as down-regulated in the tumor samples." (PMID 20799942, 2010). "In our tumor samples, we determined large amounts of the RARα, RARβ, RXRα and RXRβ transcripts." (PMID 39323992, 2024). "Tested by Spearman’s–Rho analysis, we analyzed the correlation between positive RXRα/high expressionPPARγ and various relevant clinicopathological characteristics, consist of age, tumor size (pT), lymph node status (pN), tumor grade, ER, PR, Her2, Ki-67, focality status." (PMID 35406808, 2022). "Further reports showed that overexpression of RXRα could promote tumour growth by interacting with tumour necrosis factor-alpha-induced phosphoinositide 3-kinase and NF-κB signal transduction pathways." (PMID 34870752, 2022).
tumor (continued). "Altogether, above data highlight the importance of nuclear receptor signaling in melanocytes driven by VDR and its principal heterodimer partners RXRα and RXRβ in the regulation of melanocyte homeostasis and melanomagenesis in the skin and tumor microenvironment." (PMID 34692525, 2021). "Abnormal expression and regulation of RXRα may affect a wider range of tissues, organs or tumour types." (PMID 33128348, 2020). "At present, the correlation between the expression of RXRα and tumour metastasis caused by EMT was not clearly studied." (PMID 33128348, 2020). "We speculate that RXRα may be a novel indicator of tumour metastasis or a target for inhibiting tumour metastasis by EMT induction." (PMID 33128348, 2020). "Tumor-associated GSK-3β is correlated with reduced expression of retinoic acid receptor-β (RARβ), which is caused by GSK-3β-mediated phosphorylation and heterodimerization abrogation of retinoid X receptor (RXRα) with RARα on RARβ promoter." (PMID 31938062, 2020). "Moreover, human CRC xenograft in nude mice also demonstrated the inhibition of tumor growth in an RXRα-dependent manner." (PMID 33276489, 2020). "Limited proteolytic cleavage of RXRα protein has been found in many tumor cells." (PMID 30093910, 2018). "Proteolytic cleavage of RXRα, which could reduce RXRα expression or enhance truncated RXRα expression in tumor cells, is also correlated with the development of certain malignancies." (PMID 30093910, 2018). "Collectively, we presented here several lines of evidence showing that RXRα is fine-tuned during stem cell differentiation, and its ectopic expression could trigger multiple signaling pathways on tumor suppression." (PMID 29748541, 2018). "Our data revealed the multiple impacts of RXRα—on the one hand, inhibiting cell proliferation, angiogenesis, and migration, as well as promoting tumor-suppressing mechanism (senescence); on the other hand, regulating/participating in differentiation and metabolism reprogramming." (PMID 29748541, 2018). "Therefore, EGCG is able to restore the expression of genes involved in tumor suppression such as RXRalpha (Retinoid X Receptor alpha) that are silenced by epigenetic processes in tumor cells." (PMID 28352231, 2017). "Furthermore, the luminal category of tumours frequently express the transcription factors RXRA, PPARG, FOXA1, and GATA3, which are known to have a crucial role in urothelial differentiation." (PMID 28195647, 2017). "To study whether the anti-tumour effect of K-80003 could be attributed to its effect on the subcellular localization of tRXRα in vivo, we stably transfected tRXRα or RXRα into MCF-7 cells, and the resulting stable clones were inoculated into nude mice." (PMID 28714476, 2017). "Additional studies are also necessary to elucidate the molecular mechanisms underlying the non-cell autonomous role of keratinocyitc RXRα to drive melanomagenesis in the tumor microenvironment." (PMID 29121869, 2017). "Moreover, in CRC cells, high levels of cannabinoids induced up-regulation of CB1-receptor through co-localization of PPARγ and RXRα at its promoting region, suggesting a potential epigenetic modulation in cannabinoid-mediated anti-tumor effects." (PMID 29354056, 2017). "Immunohistochemistry in tumor samples demonstrated that expression of RXRα was reduced after 4 Gy." (PMID 26500891, 2015). "We believe that decreased RXRα expression in tumor-free areas of the intestine may be a reflection of the RXRα status in other areas of the GI tract and that this molecular event may be preceding intestinal tumorigenesis in APCMin/+ mice." (PMID 26500891, 2015). "Thus, in this study, the relationship between RXRα expression and EMT level was examined, and whether RXRα expression regulated tumour metastasis." (PMID 33128348, 2020).
tumor (continued). "Altogether, above results suggest that loss of epidermal Rxrα when combined with oncogenic NRAS and activated CDK4 results in melanomagenesis, which is further accelerated by a single neonatal UVB exposure reducing the tumor latency as shown in the Kaplan Meier curve." (PMID 29121869, 2017). "Impairment of RXRα functionality may be a fundamental mechanism for tumor progression." (PMID 27167203, 2016). "The mRNA expression of RXRα, AKT1, ESR1, MAPK1, and HSP90AA1 in tumor and normal tissues was analyzed using the GEPIA database." (PMID 38835342, 2024). "The mRNA expression of RXRα, AKT1, ESR1, MAPK1, and HSP90AA1 was analyzed in different tumor tissues." (PMID 38835342, 2024). "It was notable that retinoic acid (RA) signalling TFs, including RA nuclear receptors RXRA, RXRG, and RXR-interacting partner ZNF42356, all had increased activity in these residual tumour cells." (PMID 39341888, 2024). "The tumor cells from the endometrium, esophagus, thyroid, and kidneys show dominant expressions of receptors like RXRA (Retinoid X Receptor Alpha), RXRB, PPARG, and ADORA1 (Adenosine A1 Receptor), underscoring their diverse physiological roles." (PMID 39766077, 2024). "The RXRα agonist berberine promotes KRT7-AS expression and increases PTEN levels, activates the tumor suppressive RXRα-KRT7-AS-PTEN axis, inhibits tumorigenic AKT and NF-κB signaling pathways, tumorigenesis, and promotes apoptosis." (PMID 37185462, 2023). "In this study, H. parainfluenzae and N. flavescens downregulated LXR/RXR, PPARα/RXRα and PPAR signaling, which are known to have tumor suppressive effect." (PMID 35600164, 2022). "In tumor specimens from the lung, the mRNA levels of RXR genes RXRα and RXRγ were shown to be considerably lower." (PMID 35631448, 2022). "Studies showed that retinol X receptor alpha (RXRα) and 20(S)‐Protopanaxadiol (PPD) have anti‐tumour effects." (PMID 33128348, 2020). "The LGD1069 named bexarotene, a specific ligand for RXRa, suppressed effectively both ER-positive and ER-negative tumor development in NMU tumor model." (PMID 31141879, 2019). "RXRA was reported to mediate PI3K/AKT signaling in response to stem cell differentiation and provoke tumor suppression." (PMID 30518934, 2018). "To validate that DANCR/RXRA/PIK3CA signaling pathway regulates TNBC tumor growth, we down-regulated RXRA and overexpressed PIK3CA in MDA-MB-231 and MDA-MB-468 cells with a RXRA shRNA or a PIK3CA vector." (PMID 30518934, 2018). "In this study, we demonstrated a new mechanism by which DANCR-upregulated PI3K/AKT signaling pathway through activating serine phosphorylation of RXRA protein is important for TNBC cell proliferation and tumor growth." (PMID 30518934, 2018). "Patients were given etodolac at standard doses prior to surgery, and tumor tissue samples obtained before and after the etodolac exposure were evaluated for COX-2, RXRα, and related gene expression." (PMID 26275572, 2015). "The difference in DNA methylation between RFS and n/RFS primary tumours was less considerable, although a statistically significant difference was observed for DAXX, P<0.0001; RXRA, P<0.01; C8orf46, P=0.01; NCOR2 and MSI2 (P<0.05; t-test) enhancer regions." (PMID 26169690, 2015). "According to the experimental results in vivo and in vitro, we speculated that PPI promotes the combination of RXRα and PPARγ by targeting ZBTB16, leading to the inhibitory effect on the malignant phenotype of tumor cells." (PMID 39182119, 2024). "Imatinib treatment in EV-transplanted mice showed tumor mass formation but was absent in the RXRA OE mice treated with imatinib." (PMID 37324449, 2023). "Tumor staining results appeared either negative or positive for both nuclear and cytoplasmic RXRα localizations." (PMID 34359656, 2021). "Truncated RXRα is mainly localized to the cytoplasm, regulating downstream PI3K through interactions with p85, which activates the PI3K/AKT survival pathway and promotes the disorderly proliferation of tumor cells." (PMID 34539418, 2021).
tumor (continued). "Interestingly, the consensus peaks that were specifically H3K4me1-positive in the luminal tumours were enriched for Peroxisome proliferator-activated receptor gamma (PPAR-γ or PPARG) and Retinoid X Receptor Alpha (RXRA) binding motifs." (PMID 32616859, 2020). "Using anti-phosphor-Ser/Thr (p-S/T) antibody, we confirmed that GSK-3β could induce RXRα phosphorylation in HepG2 cells and HCC tumor tissues." (PMID 31938062, 2020). "Overexpression of RXRα in myeloid cells, however, did not apparently affect tumor load as LysM-RXRα mice showed similar tumor size and multiplicity with LysM-cre mice." (PMID 30931933, 2019). "The selective effect of K-80003 is expected to lead to specific blockade of tRXRα in tumor cells without compromising the normal function of RXRα." (PMID 30931933, 2019). "Beyond those important tumor-associated pathways, the other significant pathways were also closely related to the tumor occurrence and development, such as mTOR signaling, Gap junction signaling, OC signaling, protein ubiquitination pathway, and PPAR-α/RXRα activation." (PMID 31258820, 2019). "This review analyzes the non-genomic effects of RXRα in normal and tumor cells, and discusses the functional differences based on RXRα protein structure (structure source: the RCSB Protein Data Bank)." (PMID 30093910, 2018). "Employing an APC-mutant mouse model (APCMin/+) the present study aimed to investigate the status of RXRα, an APC-independent factor involved in targeting β-catenin to UPP for degradation, in tumor-bearing and tumor-free areas of intestine after exposure to energetic 56Fe ions." (PMID 26500891, 2015). "Considering the tumour formation time and volume at these stages, we speculated that the expression of RXRα was not been significantly affected." (PMID 33128348, 2020). "Mutant RXRA protein results in increased binding to the peroxisome proliferator activator receptors (PPARs) and hyperactivation of PPAR target genes that support tumor growth, raising the potential for therapeutic intervention targeting the PPARG:RXRA heterodimer." (PMID 31805753, 2019). "We identified seven oncogenes (NRAS, EGFR, RXRA, HRAS, KRAS, AKT1, ERBB2; q<0.10) and seven putative tumor suppressor genes (ARID1A, TXNIP, CTNNB1, PIK3RI, CDKN2A, KLF5, STAG2; q<0.10) significantly regulated between tumor and control, which were formerly reported to be altered in BC." (PMID 30419021, 2018). "In addition, we measured the expression of a number of other genes in the tumours including nuclear receptors (VDR, RXRα, SXR, ER α and β), cytochrome P450 enzyme (CYP3A4), proliferation marker (MCM2, CDC6, KI67), differentiation marker (sucrase isomaltase) and angiogenesis marker (CD31)." (PMID 26238339, 2016). "Interestingly, nuclear RXRα showed a positive correlation with TIL density as only the thyroid hormone receptor TRβ did, whether the latter was expressed in the nucleus or the cytoplasm of tumor cells." (PMID 36230483, 2022). "Therefore, impaired PPARγ and/or RXRα might explain why in some cases retinoic acids failed to counteract tumor progression in some solid cancer cell lines." (PMID 32012980, 2020). "While no change in RXRα expression level was previously noted in 17 patients with CRC, our data revealed a significant increase in tumor versus normal tissue." (PMID 17767717, 2007). "Interestingly, TRAF6 interacted with tRXRα but not with RXRα, demonstrating that tRXRα activation of the IKK-NF-κB pathway is a tumor-specific event." (PMID 30931933, 2019).
infection (13 papers, 2009 to 2026). The state of being infected such as from the introduction of a foreign agent such as serum, vaccine, antigenic substance or organism. "Car was also down-regulated, but only at 8 days post-infection and Rxrα, Pxr and Lxrα followed the same trend." (PMID 31299982, 2019). "RXRα protein showed to be similarly reduced by HCMV, especially at late time points of infection, indicating that loss of RXRα might also contribute to CMV-induced vitamin-D resistance." (PMID 36146811, 2022). "In addition to VDR downregulation, we also found that its heterodimerization partner RXRα is reduced at late time points of infection." (PMID 36146811, 2022). "After infection, RXRA expression resumes, suppressing the type I IFN induction." (PMID 28241052, 2017). "In addition, infection with adenoviral RXRα induced nucleoplasmic overexpression of RXRα and resulted in apoptosis with treatment with an RXR ligand in retinoid-resistant MDA-MB-231 cells." (PMID 25778982, 2015). "shRXRγ infection appears to have partially decreased RXRα protein expression as well (likely via an indirect mechanism since shRXRγ are highly specific for RXRγ) which may contribute to the diminished LGD1069 effect." (PMID 19267912, 2009). "When cholesterol is in excess, as occurs in infection, the consequent lowering of its cellular concentration is reached by oxysterol and desmosterol binding to LXR, which forms heterodimers with RXRA in order to control the transcription activation of many genes regulating lipid metabolism." (PMID 28241052, 2017). "To determine the utility of 3D-HepLPCs-Hep as an infection model for HBV, we evaluated the expression of known host factors essential for HBV infection and replication, including the transcription factors retinoid X receptor A (RXRA), HNF4A, and the viral receptor NTCP." (PMID 30361550, 2019). "At the site of infection, expression of genes regulating vitamin A transport and metabolism (STRA6, RXRα, RBP4) increased (P ≤ 0.002) in non-lesion lung relative to diseased lung." (PMID 41476140, 2026). "PPARα/RXRα activation, Wnt/β-catenin signaling, GNRH signaling cAMP-mediated signaling, and ERK/MAPK signaling are the most prominent among the signaling pathways significantly affected by PR8 infection but were not impacted by the infection in CLIC1 KD cells." (PMID 38257829, 2024).
metabolic disease (9 papers, 2009 to 2023). A congenital disorder (due to inherited enzyme abnormality) or acquired (due to failure of a metabolically important organ) disorder resulting from an abnormal metabolic process. "A better understanding at the molecular level of the regulation of PPARγ/RXRα by their coactivators would benefit new therapeutic approaches for the treatment of metabolic diseases." (PMID 23319938, 2012). "Nuclear receptors retinoic X receptor α (RXRα) and peroxisome proliferator activated receptor γ (PPARγ) function potently in metabolic diseases, and are both important targets for anti-diabetic drugs." (PMID 22140563, 2011). "In this study, we identified the transcription factors RXRA, EGFR, and SREBP2 precursor as key transcription factors linked to lipid homeostasis and inflammatory response from liver transcriptome profile of animal models for human metabolic diseases fed with different levels of dietary soybean oil." (PMID 35725871, 2022). "Thus, RXRα agonists have great potentials for the treatment of metabolic diseases." (PMID 22140563, 2011). "In mice with metabolic disease, a constant increase in the acetylation level of FXR prevents the heterodimerization of FXR/RXRα, as well as the DNA binding of FXR/RXRα, leading to a reduction in the transactivation of FXR metabolic target genes." (PMID 38203175, 2023).
cardiovascular diseases (4 papers, 2015 to 2024). "In this sense, there is a growing interest in the nuclear transcription factor retinoid X receptor alpha (RXRα) as a regulator of energy metabolism in cardiovascular diseases." (PMID 38279217, 2024). "Besides, mi-26b, which was confirmed as a protective gene in cardiovascular diseases, was found to connect RXRA with ULK1 in the coregulatory network." (PMID 37596272, 2023). "However, whether RXRα can directly regulate Nrf2 in cardiovascular diseases has not been reported." (PMID 36555577, 2022).
kidney (2 papers, 2015 to 2025). "Notably, our animal studies demonstrated that RXRα deficiency exacerbated the deposition of CaOx crystal and increased kidney injury, whereas activation of RXRα markedly reduced CaOx crystal deposition and mitigated kidney damage." (PMID 40091688, 2025).